CD4 (CD4 molecule)
Diseases named in the same sentence as CD4 in open-access papers (continued):
Sharing a sentence is not in itself a finding about the gene and the disease.
malaria (continued). "In subgroup analyses, malaria occurred at a statistically significantly higher rate in the CTX discontinuation arm than in the CTX continuation arm across categories of enrollment CD4 count and ART duration at enrollment." (PMID 26731191, 2016). "Indeed, we found that the PD1+CTLA4+CD4+ Teff cells in our malaria patients produced the regulatory cytokine IL10 in response to P. falciparum-antigens." (PMID 27802341, 2016). "Importantly, patients with severe cerebral malaria showed a higher frequency of CTLA4+CD4+ T cells than patients with uncomplicated malaria." (PMID 27802341, 2016). "Data from this trial were used to investigate the effect of CD4 count on the incidence of malaria, and whether the effect of CD4 count on malaria differed by CTX use." (PMID 27417903, 2016). "Prior studies evaluating fetal CD127+ CD4 T cells have not found an association with malaria exposure, but in these studies PM was diagnosed based only on less sensitive blood smears." (PMID 27717402, 2016). "However, IFN-γ and TNF are among the major cytokines shown to be associated with immunity against malaria, hence the study provides valid insight on the effect of CTX prophylaxis on antigen-specific CD4+ T cells immune responses." (PMID 27165269, 2016). "Thus, we examined possible CD4 T cell-intrinsic impacts of type I IFN signaling during experimental malaria." (PMID 27732671, 2016). "Furthermore, recent research in malaria has established that CD4+ and CD8+T cells experience exhaustion, a dysfunction of T-cells preventing optimal control of chronic infections." (PMID 27900319, 2016). "We initially hypothesized that the induction of coinhibitory receptors, primarily CTLA4 and PD1, is an important and adaptable mechanism by which CD4+ T cell responses in malaria are downregulated." (PMID 27802341, 2016). "CD4 T cell-dependent antibody responses are essential for limiting Plasmodium parasite replication and the severity of malaria; however, the factors that regulate humoral immunity during highly inflammatory, Th1-biased systemic infections are poorly understood." (PMID 27732671, 2016). "Likewise and as also suggested before, a slight decrease in the blood proportion of CD8+ and CD4+ T cells was observed in severe malaria patients and both subsets of T lymphocytes underwent robust activation, proliferation and differentiation." (PMID 27792766, 2016). "Studies from experimental malaria challenge showed that even a single exposure to malaria induced robust CD4+ T cell responses producing IFN-y that could be detected 14 months post infection in the absence of further exposure." (PMID 27165269, 2016). "Moreover, malaria infection inhibits immune responses to the parasite itself, and CD4+ T cells from malaria-infected mice and humans have defects in the ability to produce IL-2 in response to T-cell receptor stimulation." (PMID 27867385, 2016). "We therefore asked whether the malaria-induced PD1+CTLA4+CD4+ T cells could suppress other CD4+ T cells." (PMID 27802341, 2016). "Results from this study are consistent with those of a recent unblinded trial of CTX discontinuation in adults on ART in Kenya, which found that the effect of stopping CTX on malaria was similar in participants with CD4 count ≤600 at enrolment and those with CD4 >600." (PMID 27417903, 2016). "In keeping with previous reports of exposure dependent impairment of T cell proliferation, P. falciparum-specific CD4+ T cell proliferation in continually exposed children was not significantly different from the level of proliferation observed in malaria-naïve children." (PMID 27660116, 2016). "Thus, IL-27-producing regulatory CD4+ T cells, designated Tr27 cells, play a critical role in the regulation of protective immune responses against malaria parasites." (PMID 27867385, 2016).
malaria (continued). "Findings include that while Tregs were higher among infants with early/remote malaria exposure, active placental infection with persistence of plasmodial DNA at the time of delivery was associated with expansion of activated CD127+ CD4 T cells resembling effector memory T cells." (PMID 27717402, 2016). "However, further experiments will be required to examine the effect of ICOS-signalling on CD4+ T-cell trafficking in the spleen during experimental malaria." (PMID 27812214, 2016). "Differences in the immune phenotypes of the DBA/2 strain, such as resistance to malaria, have been largely attributed to B cell-dependent mechanisms, but the activation score here indicates that naïve CD4 T cells from DBA/2 mice are skewed toward an activated phenotype." (PMID 27376549, 2016). "Based on similar observations in a type 1 response in a mouse model of malaria, this may well be a universal phenomenon during primary activation of CD4+ T lymphocytes." (PMID 27176874, 2016). "Analysis of CD4+ T cells also demonstrated that P. vivax-infected donors had a higher percentage of circulating cells in late apoptosis (Annexin V+/PI+) (14.86%) compared to malaria-naive donors (1.29%) (p < 0.0001)." (PMID 25559491, 2015). "In rural Gambia, the percentage and absolute count of FoxP3+CD127low CD4 T cells were shown to increase following the malaria transmission season, and are significantly higher among malaria-exposed rural Gambians than among ethnically matched urban Gambians with no malaria exposure." (PMID 26182204, 2015). "Additionally, the frequency of CD4+CD25hi+ T cells was higher in both age-matched acute uncomplicated malaria (n = 26) and eBL (n = 14) patients compared to healthy controls (n = 19; p = 0.000 and p = 0.027, respectively)." (PMID 28536409, 2015). "First, this was a surveillance study that could not analyze in details the complex interplay of the effects of HIV on malaria by evaluating levels of CD4+/CD8+ T cells ratio and HIV disease stage." (PMID 26173396, 2015). "It is possible that antigen persistence and, consequently, TCR: MHC- (major histocompatibility complex-) peptide complex interactions play a role by itself in the maintenance of CD4+ TM cells, and this has been a subject of interest for malaria as well as for other infections." (PMID 26509177, 2015). "Among these effector cells, memory CD4+ T (TM) cells are considered a crucial population for the protective immunity against bacterial infections, viral infections, and protozoan infections such as malaria." (PMID 26509177, 2015). "Neither lower pre-entry CD4+ T-cell counts nor higher plasma HIV-1 RNA levels at study entry were significantly associated with either PCR positivity or clinical malaria." (PMID 26053030, 2015). "This suggests that heavy prior exposure to malaria may limit the propensity of CD4 cells to differentiate into Tregs upon re-encounter with parasite antigens." (PMID 26182204, 2015). "Nevertheless, it is still unclear whether DCs are unique in their ability to initiate CD4+ T cell responses to Pc blood-stages in the spleen, as observed in Plasmodium berghei(Pb) malaria." (PMID 25658925, 2015). "CD4+cells from individuals with fewer previous episodes of malaria were more inflammatoryand had greater TNF production, whereas responses from CD4+ T-cells fromsubjects with more frequent previous episodes of malaria were more typical of regulatoryT-cells in that they produced IL-10." (PMID 26676319, 2015). "For example, phase IIa clinical trials for the RTS,S pre-erythrocytic malaria vaccine candidate showed a correlation between prolonged CD4+ and CD8+ T cell IFN-γ responses against a malaria-specific protein and protection upon challenge infection in human volunteers." (PMID 26426121, 2015). "Our data show a significant increase in the frequency of CD4+CD25hi+ cells in both malaria and eBL." (PMID 28536409, 2015).
malaria (continued). "T-lymphocytes count assessment carried out among different groups of the study participants revealed that, except helper T-lymphocytes or CD4+ count among khat chewer malaria patients’, khat did not cause any effect on others." (PMID 26173100, 2015). "Consistent with the immunologic polarization concept for different clinical forms of malaria, a smaller increase in memory CD4+ T cells is found among children with uncomplicated malaria, while the median ratio for severe malarial anemia is the same as that for controls." (PMID 26581890, 2015). "Using the same system, we investigated the phenotype of CD4+ T cells specific for the DBLα-tag identified in each clinical isolate for 35 children suffering from acute malaria and who were under active surveillance for acute malaria episodes." (PMID 24453249, 2014). "This reduction might be attributable to malaria-mediated activation and apoptotic induction of memory CD4+ T cells." (PMID 25487036, 2014). "Both IL-10-producing CD4+ T cells and IFNγ-producing CD4+ T cells were present at higher frequencies among children with a higher prior incidence of malaria (≥2 episodes ppy) than among those with a lower prior incidence (<2 episodes ppy, P<0.001 and P = 0.02, respectively)." (PMID 24415936, 2014). "These CD4+ T cells may play important immunomodulatory roles in the pathogenesis of malaria in childhood." (PMID 24415936, 2014). "In univariate Cox proportional hazards analysis evaluating time to next episode of malaria, a higher frequency of CD4+ T cells producing any IFNγ or IL10, or the combinations IFNγ+/IL-10+/TNFα− and IFNγ−/IL-10+/TNFα− was associated with a significantly increased hazard of malaria (left columns)." (PMID 24415936, 2014). "Magnitude of malaria-specific CD4+ T cell responses and protection from symptomatic malaria." (PMID 24415936, 2014). "IL-10 can also be induced in IL-17-producing CD4+ T-cells, as yet by unknown pathways, and thus, IL-10 may be a more general mechanism for regulating any subset of CD4+ T-cells in malaria." (PMID 25628621, 2014). "Recently, the Th17 subset of CD4+ T-cells, defined by the expression of the transcription factor RORγt, has gained attention among malaria researchers because of its role in autoimmune diseases and chronic inflammation and in responses to extracellular pathogens such as bacteria and fungi." (PMID 25628621, 2014). "We magnetically isolated CD4+ T cells collected after the resolution of febrile malaria and cultured these cells with autologous APCs collected at the healthy baseline before the malaria season or after the resolution of febrile malaria." (PMID 24743880, 2014). "One mechanism of self-regulation by CD4+ Th1 cells in malaria is the induction of IL-10." (PMID 25628621, 2014). "Additionally, malaria induced histone acetylation and activation of NF-kappaB (NF-κB) in resting CD4+ T cells." (PMID 25487036, 2014). "This pattern could be explained by the fact that subjects with advanced clinical stages or a low CD4 count had poor immunity against malaria and other infections were therefore more vulnerable to becoming anaemic." (PMID 24761799, 2014). "However, studies have shown that rates of malaria episode in HIV-infected individuals increase with falling CD4 T-cell count." (PMID 24729787, 2014). "Further studies analyzing the relationship between Ag-specific memory B cells, Ab levels and different CD4+ T cell subsets including Th2 and Tfh T cells are required to elucidate these interactions and their relevance for clinical immunity to malaria in humans." (PMID 24453249, 2014). "CD4+ T cell responses were measurable in nearly all children, with the majority of children having CD4+ T cells producing both IFNγ and IL-10 in response to malaria-infected red blood cells." (PMID 24415936, 2014). "Also during malaria caused by P. falciparum, IFN-γ can be produced by cells from both innate and adaptive immune system NK cells, gamma-delta T cells, and CD4+ and CD8+ alpha-beta T cells." (PMID 24741587, 2014).
malaria (continued). "However, the apoptosis levels of CD4+ TCM cells in the ART + Pc group were higher than those in the ART group during the malaria phase (especially during the acute phase, from weeks 49–53; means of 8.25% and 6.56%, respectively; P = 0.12)." (PMID 25487036, 2014). "More detailed understanding of these mechanisms may lead to techniques to optimally deliver practical subunit vaccines, bringing CD4+ T cell help to anti-malaria CD8+ T cells and resulting in long-lived protective immunity at the liver-stage." (PMID 25426113, 2014). "To identify CD4+ T cell responses to PfEMP1 children had encountered during an acute malaria episode, we expressed DBLα-tags representing the dominant PfEMP1 on a parasite isolate and stimulated PBMCs from the child who donated the parasites with this homologous DBLα-tag." (PMID 24453249, 2014). "The most recent studies suggest that CD4+ T-cell activation with overlapping characteristics of different Th subsets is the norm rather than the exception, and this is likely to be reflected in complex diseases such as malaria." (PMID 25628621, 2014). "The fact that malaria subjects with the highest CD4+ cell percentages at enrollment experienced the largest RNA declines is also consistent with the hypothesis that CD4+ cell activation is partly responsible for raised HIV RNA levels." (PMID 23327493, 2013). "Using malaria as a model systemic pro-inflammatory infection, we demonstrate that the aberrant accumulation of CD4+ T cells in the liver of infected IL27R−/− (WSX-1−/−) mice is a result of differences in cellular recruitment, rather than changes in T cell proliferation or cell death." (PMID 24244314, 2013). "Alternatively, malaria patients with higher CD4+ cell percentages may be better able to control either infection, resulting in a more rapid decline in RNA." (PMID 23327493, 2013). "In support of this latter hypothesis, we have shown that splenic CD4+ T cells from malaria-infected WSX-1−/− mice express higher levels of CCR5 than cells from WT mice and are consequently hyper responsive to CCR1 and CCR5 ligands." (PMID 24244314, 2013). "Similarly, significantly higher frequencies of malaria specific splenic effector CD4+ T cells produced IFN-γ in WSX-1−/− mice than in WT mice on day 14 of infection, corresponding with higher plasma levels of IFN-γ." (PMID 23593003, 2013). "Therefore, the aim of this study was to investigate the expression of ANXA1 in CD4+, CD8+ T cells, regulatory T cells (Treg) and quantification of the cytokine IL-10 in plasma from patients with malaria caused by P. vivax." (PMID 24359168, 2013). "Malaria is associated with an increase in HIV viral load and a fall in CD4-cell count." (PMID 24172232, 2013). "There is a general consensus that HIV-uninfected or immunocompetent HIV-infected women with relatively good levels of CD4+ T cells (> 350 cells/μl of blood) can mount protective immune responses when exposed to malaria infection, and this can limit malaria and other infections." (PMID 24007344, 2013). "For diseases where vaccine-induced immune responses may be boosted by natural exposure, such as malaria, inclusion of pathogen-specific CD4+ T cell epitopes is desired." (PMID 22936972, 2012). "We wondered whether children suffering from severe, life-threatening malaria differed with respect to the magnitude, duration or type of CD4+ T-cells responses specific for the homologous DBLα-tag from children suffering from moderate malaria." (PMID 22272280, 2012). "In that previous report, we were unable to assess polyfunctionality of T cell phenotypes, but nevertheless identified an association between the frequency of CD4+ T cells producing at least TNF on stimulation with CSP peptides and protection against clinical malaria." (PMID 23300801, 2012). "Memory CD4+ T-cells have been an active area of inquiry in the malaria field." (PMID 22745697, 2012).
malaria (continued). "Additionally, acute malaria is associated with an increase in HIV viral load and a steeper decline in CD4 cell count, and these viral load and CD4 count changes can take several weeks to recover after successful malaria therapy." (PMID 22943054, 2012). "This regimen may provide high-level protection against malaria due to induction of strong CD8+/CD4+ T cell responses and strong antibody responses as observed in preclinical studies." (PMID 22003383, 2011). "In the current study, we evaluated the role of CD4+ T cell help on the development of functional anti-malaria effector and memory CD8+ T cells by using Thy-1 allelic mismatched T cells so that survival could be measured independently of effector function." (PMID 21245909, 2011). "Hence, B cells and malaria specific antibodies are, in addition to CD4+T cells, required for effective antimalarial immunity." (PMID 21687602, 2011). "In a malaria vaccine study in TheGambia strong CD4 and weak CD8 T cell responses were induced by two 1 mg dosesof a DNA vaccine given intramuscularly, followed by one dose of3.0×107 pfu (plaque forming units) MVA vaccine givenintradermally at intervals 3 weeks apart." (PMID 21347224, 2011). "Such cells may be associated with protective immunity (leishmaniasis, HIV) although the role of either CD4+ or CD8+ multifunctional T cells in malaria, though suggested, remains to be proven." (PMID 22003383, 2011). "Protective immunity against blood-stage malaria is dependent on CD4 T cells and B cells." (PMID 22053177, 2011). "Thus, CD8+ T cell-mediated control of liver stage malaria parasites is critically dependent on CD4 help." (PMID 21245909, 2011). "The majority of CD4+ CD25high cells were found to express Foxp3, suggesting that natural Treg cells may negatively affect natural acquired immunity to malaria." (PMID 20442856, 2010). "Here, we have used a mouse model of malaria, P. chabaudi, to investigate whether Plasmodium-specific CD4+ T cell memory develops in a blood-stage infection." (PMID 21124875, 2010). "In order to identify malaria-specific CD4+ T memory cells during malaria, we have followed the response of P. chabaudi-specific transgenic CD4+ T cells, which carry a TCR recognising a peptide of Merozoite Surface Protein-1 (B5 Tg,), throughout a blood-stage infection of P. chabaudi in mice." (PMID 21124875, 2010). "The lack ofcomparable CD4+ counts makes it difficult to conclude whether the baseline immunological state has a bearing on the severity of the malaria and the log increase in viral load." (PMID 21918698, 2010). "We first asked whether Foxp3 expressing CD4 T cells could be induced by culturing PBMCs of healthy Australian blood bank donors with malaria-infected trophozoite stage RBCs (iRBCs)." (PMID 19680449, 2009). "An inverse relationship was found between incidence of severe malaria and CD4+ T lymphocyte counts." (PMID 19680452, 2009). "The extremely high proportion of low CD4 count in both case-patients and controls with uncomplicated malaria might be confounded by a temporary malaria-induced reallocation of specific T-cells." (PMID 19402961, 2009). "Focusing on the few studies of children, those with a higher incidence of malaria had higher frequencies of CD4+ CD25hi regulatory T cells that prevented the protective IFN-γ responses characteristically observed in adults who have developed anti-malarial immunity." (PMID 19691558, 2009). "Therefore, in vitro assays reflecting in vivo processes as closely as possible are needed to examine the mechanisms involved in the malaria parasite-mediated generation of CD4+CD25+Foxp3+ human T cells." (PMID 19680449, 2009). "Although the extremely high proportion of a low CD4 count in patients in our study might have been confounded by a temporary malaria-induced reallocation of specific T cells; 70% had a CD4 count <350/μL 1 month after successful treatment." (PMID 19402961, 2009).